TRPA1 (transient receptor potential cation channel subfamily A member 1)
Description:
Ligand-activated Ca(2+)-permeable, nonselective cation channel involved in pain detection and possibly also in cold perception, oxygen concentration perception, cough, itch, and inner ear function. Has a relatively high Ca(2+) selectivity, with a preference for divalent over monovalent cations (Ca(2+) > Ba(2+) > Mg(2+) > NH4(+) > Li(+) > K(+)), the influx of cation into the cytoplasm leads to membrane depolarization. Has a central role in the pain response to endogenous inflammatory mediators, such as bradykinin and to a diverse array of irritants. Activated by a large variety of structurally unrelated electrophilic and non-electrophilic chemical compounds, such as allylthiocyanate (AITC) from mustard oil or wasabi, cinnamaldehyde, diallyl disulfide (DADS) from garlic, and acrolein, an environmental irritant. Electrophilic ligands activate TRPA1 by interacting with critical N-terminal Cys residues in a covalent manner. Non-electrophile agonists bind at distinct sites in the transmembrane domain to promote channel activation. Also acts as an ionotropic cannabinoid receptor by being activated by delta(9)-tetrahydrocannabinol (THC), the psychoactive component of marijuana. May be a component for the mechanosensitive transduction channel of hair cells in inner ear, thereby participating in the perception of sounds (By similarity).
Synonyms: p120; ANKTM1; FEPS; FEPS1
Tractability: Small molecule: an approved drug acts on it; a structure with a bound ligand is known; a high-quality ligand is known; it belongs to a druggable protein family. Antibody: UniProt places it where antibodies can reach, with high confidence; its Gene Ontology location is reachable by antibodies, with high confidence; UniProt predicts a signal peptide or a membrane-spanning region. PROTAC: a small molecule that binds it is known.
Target class: Voltage-gated ion channel; Ion channel; Transient receptor potential channel
Chemical probes: A-967079 (high quality), BAY-390 (high quality), CHEMBL3298923 (high quality), CHEMBL3299022
Gene: Protein-coding gene on chromosome 8 (72,019,608 to 72,089,998, reverse strand). Ensembl gene ENSG00000104321.
Subcellular location: Cell membrane
Pathways (Reactome):
Transport of small molecules: TRP channels
Gene Ontology:
Molecular function: identical protein binding; intracellularly gated calcium channel activity; temperature-gated cation channel activity; calcium channel activity; channel activity; gated channel activity; monoatomic ion channel activity; osmolarity-sensing monoatomic cation channel activity; voltage-gated calcium channel activity
Biological process: calcium ion transmembrane transport; cellular response to hydrogen peroxide; intracellular calcium ion homeostasis; protein homotetramerization; response to cold; sensory perception of pain; calcium ion transmembrane import into cytosol; cell surface receptor signaling pathway; cellular response to food; detection of chemical stimulus involved in sensory perception of pain; monoatomic ion transport; thermoception; calcium-mediated signaling; cellular response to caffeine; cellular response to carbon dioxide; cellular response to cold; cellular response to heat; cellular response to oxygen-containing compound; cellular response to stress; cellular response to toxic substance; detection of mechanical stimulus involved in sensory perception; positive regulation of insulin secretion involved in cellular response to glucose stimulus; positive regulation of monoatomic anion transport; regulation of blood circulation; regulation of neuronal action potential; and 5 more
Cellular component: plasma membrane; apical plasma membrane; axon; membrane; stereocilium bundle
Genetic constraint (gnomAD): Loss-of-function variants: 80 observed, 90.6 expected, observed/expected ratio (o/e) 0.88, 90% interval 0.74 to 1.06. The upper end of that interval is the gene's LOEUF score, 1.06, which puts it in group 4 of 6, group 1 being the genes least tolerant of losing a copy. Missense variants: 1,057 observed, 1,158.8 expected, observed/expected ratio (o/e) 0.91, 90% interval 0.87 to 0.96. Synonymous variants: 378 observed, 395.66 expected, observed/expected ratio (o/e) 0.96, 90% interval 0.88 to 1.04.
Homologues: Orthologues: chimpanzee TRPA1 (99% identical), macaque TRPA1 (97% identical), dog TRPA1 (83% identical), pig TRPA1 (81% identical), rabbit TRPA1 (81% identical), mouse Trpa1 (80% identical), rat Trpa1 (80% identical), guinea pig TRPA1 (68% identical), tropical clawed frog trpa1 (52% identical), zebrafish trpa1a (48% identical), zebrafish trpa1b (46% identical), Drosophila melanogaster TrpA1 (34% identical), and 1 more.
Diseases named in the same sentence as TRPA1 in open-access papers:
TRPA1 is named in the same sentence as 315 diseases in open-access papers, as found by Europe PMC text mining. Sharing a sentence is not in itself a finding about the gene and the disease. The quoted sentences say what the papers report.
migraine (79 papers, 2012 to 2025). "It has recently been shown that TRPA1 contributes to migraine-associated hypersensitivity, since the TRPA1 antagonist, ADM_12, prevented the nitroglycerine-induced hyperalgesia in both the acute and chronic migraine models." (PMID 36982450, 2023). "Out of the six TRP subfamilies, only TRP melastatin (eight members, TRPM1-8), TRP vanilloid (six members, TRPV1-6), and TRP ankyrin (one member, TRPA1) are associated with migraines." (PMID 36831105, 2023). "In this review, we focus on the importance of a possible functional modification of TRPA1 in the pathomechanism of migraine and associated hypersensitivity." (PMID 36982450, 2023). "The current data reviewed here indicate that TRPA1 is functionally important in inflammation-induced hyperalgesia in the periphery, which also implies its role in migraine-associated hypersensitivity." (PMID 36982450, 2023). "Preclinical data point to the contribution of transient receptor potential ankyrin 1 (TRPA1) channels to the complex mechanisms underlying migraine pain." (PMID 36430567, 2022). "It was also established that rs959976 is associated with migraine onset before the age of 15 and can modulate the response of TRPA1 to coal fly ash." (PMID 33567636, 2021). "In fact, SFKs have similar roles to TRPA1 in mediating multiple migraine-associated events including CSD, brain perfusion, nociceptive behavior, CGRP expression and release." (PMID 34830154, 2021). "A growing number of studies have linked TRP channels with migraine, specifically TRPA1 and TRPV1 channels which are expressed in trigeminal sensory neurons." (PMID 34790097, 2021). "We propose that there is a positive feedback loop among these signals by which TRPA1 exerts in stress-associated migraine." (PMID 30841847, 2019). "TRPA1 activation by these mediators can release further headache-provoking substances and there is an epidemiological association between environmental exposure to TRPA1 activators and migraine." (PMID 31547502, 2019). "This study aimed to assess the effect of ibuprofen and paracetamol on TRPA1, an ion channel implicated in the pathophysiology of migraine with migraine triggers such as acrolein and umbellulone as known TRPA1 agonists." (PMID 30238173, 2018). "Umbellulone is another irritant in the environment and an established migraine trigger that has also been shown to drive human and rodent TRPA1 channels in vitro, evoke neurogenic vasodilation and inflammation as well as migraine-associated hypersensitivity." (PMID 30388732, 2018). "In this respect, it is of interest that a number of compounds, recently identified as TRPA1 agonists, including cigarette smoke, ammonium chloride, formaldehyde, chlorine, garlic and others are known triggers of migraine attacks in susceptible individuals." (PMID 23941062, 2013). "In contrast, a series of observational findings has recently been obtained regarding a possible association between TRPA1 and migraine." (PMID 23941062, 2013). "Furthermore, TRPA1 activation can also induce apoptosis and its dysfunction is associated with migraine, trigeminal nociception, glial inflammation in Alzheimer’s disease, inflammatory bowel disease, peripheral pain, lung disorders." (PMID 40282211, 2025). "The unique TRPA member (TRPA1) is a Ca2+ channel, contains 16 ankyrin repeats and is expressed in sensory neurons of skin and lung where it is responsive to mechanical stress, and in the brain where plays a role in nociception directly linked to migraine." (PMID 40282211, 2025). "Recent studies on TRPA1 exploring the TRPA1-mediated glial–neuronal interactions, the modification of the channel, or its association with other pain-related receptors, provide new insights into the pathomechanism of migraine." (PMID 36982450, 2023). "Additionally, the monoterpene umbellulone, produced by Umbellularia californica, has been linked to migraine induction in humans and reported as a TRPA1 activator." (PMID 37175602, 2023).
migraine (continued). "TRPA1 is also linked to migraine through its endogenous activators, such as reactive oxygen species (ROS), reactive prostaglandins, and nitric oxide (NO), all of which are well-known to play a role in migraine attacks." (PMID 37175602, 2023). "The involvement of TRPA1 in neurogenic inflammation, important in migraine pathogenesis, may be linked with its functioning in immune cells." (PMID 37326902, 2023). "The findings of the present study contribute important information by showing that glial activation via TRPA1 channels may contribute to trigeminal hyperalgesia associated with migraine-like pain." (PMID 36430567, 2022). "As other nocisensitive channels implicated in migraine, TRPA1 and P2X3 also reportedly transfer to the surface of sensitised nociceptors, BoNTs could potentially provide more broadly effective analgesia than selective antagonism of any single channel." (PMID 35055082, 2022). "Additionally, dural injection of TRPA1 agonists causes migraine-related periorbital mechanical allodynia (PMA)." (PMID 34451927, 2021). "RNS can also act as TRPA1 agonists, and have been linked to headaches and migraine development." (PMID 31336748, 2019). "Although the TRPA1 activator mustard oil had been used as a probe to cause pain responses from the meninges in rodents for a number of years, investigation of this channel in migraine expanded following a couple of key studies." (PMID 30970581, 2019). "Associated release of neuropeptide CGRP from TRPV1/TRPA1 positive peptidergic nerve fibers should further support both neuronal sensitization and the long-lasting nociceptive firing underlying migraine pain." (PMID 28798669, 2017). "TRPV1, TRPM8 and TRPA1 have all been linked to migraine pathophysiology." (PMID 27854251, 2016). "In addition, TRPA1 polymorphism has been linked to migraine generation." (PMID 36614146, 2022). "However, transient receptor potential (TRP) channels have been repeatedly linked to the disorder, including TRPV1, TRPV4, TRPM8, and TRPA1, based on their activation by pathological stimuli related to attacks, or their modulation by drugs/natural products known to be efficacious for migraine." (PMID 30970581, 2019). "Furthermore, TRPA1 activation causes release of CGRP that is considered a pro-migraine peptide." (PMID 30388732, 2018). "The involvement of CGRP in migraine pathogenesis is well-established, and the role of TRPA1 in CGRP release further emphasizes its importance in migraine." (PMID 40391079, 2025). "TRPA1‐mediated neurogenic inflammation in migraine pathogenesis is regulated by these epigenetic modifications." (PMID 41399206, 2025). "In fact, these channels are activated by a variety of migraine triggers, and the expression of the TRPA1 gene undergoes variations by DNA methylation, histone modifications, miRNAs, long ncRNAs and circular RNAs." (PMID 40711166, 2025). "Emerging evidence highlights the role of TRPA1 in glial activation, particularly in astrocytes, as a driver of neuroinflammatory processes contributing to migraine." (PMID 41399206, 2025). "This bidirectional relationship between epigenetic regulation and neurogenic inflammation underscores TRPA1 as a potential therapeutic target for the intervention of migraine." (PMID 41399206, 2025). "Umbellulone (UMB), is a volatile activator of TRPA1 that is known to play a crucial role in migraine progression." (PMID 39390364, 2024). "That study showed the critical involvement of TRPA1 in the pathogenesis of migraine and its potential to neutralize hyperalgesia at the trigeminal level." (PMID 39064963, 2024). "In this narrative review, we present information on the mutual connections between oxidative stress and migraine, the structure and functions of TRPA1, and its role in oxidative stress sensing and defense in some pathologies, including migraine." (PMID 39064963, 2024).
migraine (continued). "Our novel migraine model exhibited that the TRPA1 agonist umbellulone selectively induced cephalic and extracephalic allodynia in CFA-primed animals, corroborating the observations from the Durham and Porreca research groups." (PMID 38380374, 2024). "The fact that UMB is capable of inducing light aversion offers new insight into the critical role of TRPA1 in migraine pathogenesis." (PMID 39390364, 2024). "Headache, one of the main symptoms of migraines, can appear in the form of pain; the pain detection function, a key feature of TRPA1, is noteworthy in the signaling pathway related to the occurrence of these headaches." (PMID 39273183, 2024). "This review will focus on the involvement of TRPA1 in migraine-related effects, first pain transmission, neurogenic inflammation, and vasodilation." (PMID 39064963, 2024). "Parthenolide, which inhibits TRPA1-mediated pain responses, has anti-inflammatory effects and prevents migraines." (PMID 39273183, 2024). "Recently, the transient receptor potential ankyrin 1 (TRPA1) has gained more attention in migraine-related research." (PMID 36982450, 2023). "Pre-clinical studies have also shown that several TRPA1 antagonists and genetic deletion are effective in reducing migraine-like symptoms such as allodynia." (PMID 37175602, 2023). "In migraine, several agents targeting TRPA-1 and TRPV-1 receptors can trigger or preempt headache attacks." (PMID 36835524, 2023). "The fact that TRPA1 activation is involved in the trigeminal nociceptive functions has suggested its presumptive role in the development of migraine-related intracranial hypersensitivity." (PMID 36982450, 2023). "On the other hand, herbal extracts and pharmaceuticals efficacious for treating migraines have been shown to antagonise TRPA1." (PMID 36674850, 2023). "Ligustilide (Angelica sinensis), another migraine-abortive agent, has also been proven to act as a TRPA1 desensitizing agonist." (PMID 36982450, 2023). "Although there are many reviews on the TRPA1 channel, addressing mainly its role in pain transmission and inflammation, few of them deal with migraine, despite a mechanistic connection between TRP ion channels and CGRP signaling." (PMID 37326902, 2023). "A recent study reported an altered synthesis of trigeminal TRPA1 triggered by chronic exposure to acrolein and suggests a key role of this process in the chronification of migraine." (PMID 36982450, 2023). "Several migraine triggers, such as formalin, cigarette smoke, and even tear gas, have been shown to act through the TRPA1 channel." (PMID 36982450, 2023). "The TRPA1/NOX pathway in trigeminal ganglion (TG) neurons is also involved in triglyceride-induced migraine, and ectopic pain is attenuated in TRPA1-KO mice or the selective deletion of TRPA1 in sensory neurons." (PMID 36875034, 2023). "A recent study demonstrated that an increased expression of CGRP in the trigeminal ganglion is mediated by TRPA1 in both acute and chronic migraine models." (PMID 36982450, 2023). "Several studies have already pointed out the relevance of TRPA1 in the pathomechanism of pain sensation and migraine." (PMID 36982450, 2023). "It is proposed by Pierangelo Geppetti that TRPA1 is activated by pain-inducing exogenous and endogenous drugs that release pro-migraine peptides and calcitonin gene-related peptides through this neuronal pathway, which mediated the onset of headache." (PMID 37025492, 2023). "Dural application of both agonists in in vivo behavioral model of migraine-related allodynia induced robust time-related tactile facial and hind paw allodynia that was weakened by pretreatment with the TRPA1 antagonist HC-030031." (PMID 37326902, 2023). "This narrative/perspective review presents information on the structure and functions of TRPA1 as well as role of its epigenetic connections in pain transmission and potential in migraine therapy." (PMID 37326902, 2023).